GRK1 (G protein-coupled receptor kinase 1)
Description:
Retina-specific kinase involved in the signal turnoff via phosphorylation of rhodopsin (RHO), the G protein-coupled receptor that initiates the phototransduction cascade. This rapid desensitization is essential for scotopic vision and permits rapid adaptation to changes in illumination (By similarity). May play a role in the maintenance of the outer nuclear layer in the retina (By similarity).
Synonyms: RK; RHOK; GPRK1
Tractability: Small molecule: a high-quality ligand is known; it belongs to a druggable protein family. PROTAC: a small molecule that binds it is known.
Target class: AGC protein kinase GRK family; Kinase; AGC protein kinase group; AGC protein kinase GRK subfamily; Enzyme; Protein Kinase
Gene: Protein-coding gene on chromosome 13 (113,667,219 to 113,737,736, forward strand). Ensembl gene ENSG00000185974.
Subcellular location: Membrane; Cell projection, cilium, photoreceptor outer segment
Subcellular location (Human Protein Atlas): Principal piece
Pathways (Reactome):
Sensory Perception: Inactivation, recovery and regulation of the phototransduction cascade
Gene Ontology:
Molecular function: rhodopsin kinase activity; protein kinase activity; ATP binding; G protein-coupled receptor kinase activity; protein serine/threonine kinase activity
Biological process: regulation of opsin-mediated signaling pathway; G protein-coupled opsin signaling pathway; regulation of G protein-coupled receptor signaling pathway; regulation of signal transduction; visual perception; response to light stimulus; signal transduction
Cellular component: cytoplasm; membrane; photoreceptor disc membrane; photoreceptor outer segment
Genetic constraint (gnomAD): Loss-of-function variants: 17 observed, 23.11 expected, observed/expected ratio (o/e) 0.74, 90% interval 0.5 to 1.1. The upper end of that interval is the gene's LOEUF score, 1.1, which puts it in group 4 of 6, group 1 being the genes least tolerant of losing a copy. Missense variants: 382 observed, 394.59 expected, observed/expected ratio (o/e) 0.97, 90% interval 0.89 to 1.05. Synonymous variants: 170 observed, 155.79 expected, observed/expected ratio (o/e) 1.09, 90% interval 0.96 to 1.24.
Gene-disease validity (ClinGen):
ClinGen rates the evidence that GRK1 causes each of these diseases.
Oguchi disease (autosomal recessive): Definitive. Oguchi disease is an autosomal recessive retinal disorder characterized by congenital stationary night blindness and the Mizuo-Nakamura phenomenon.
Homologues: Orthologues: chimpanzee GRK1 (99% identical), macaque GRK1 (93% identical), dog GRK1 (88% identical), rat Grk1 (86% identical), mouse Grk1 (86% identical), guinea pig GRK1 (84% identical), pig GRK1 (84% identical), zebrafish grk1a (67% identical), tropical clawed frog grk1 (65% identical), Drosophila melanogaster Gprk2 (45% identical), Caenorhabditis elegans grk-1 (44% identical). Paralogues in human: GRK6 (47% identical), GRK4 (46% identical), GRK5 (45% identical), GRK7 (45% identical), GRK2 (33% identical), GRK3 (33% identical), RSKR (16% identical).
Diseases named in the same sentence as GRK1 in open-access papers:
GRK1 is named in the same sentence as 45 diseases in open-access papers, as found by Europe PMC text mining. Sharing a sentence is not in itself a finding about the gene and the disease. The quoted sentences say what the papers report.
Oguchi disease (16 papers, 2009 to 2026). "–31 GRK1 mutations cause Oguchi disease (a night blindness disorder) by preventing proper deactivation of photoactivated RHO, resulting in profoundly delayed rod cell recovery and subsequent retinal degeneration." (PMID 41805095, 2026). "Oguchi disease is a rare form of autosomal recessive CSNB arising from biallelic pathogenic variants in GRK1 or SAG." (PMID 40013354, 2025). "This symptomatology is also characteristic of vitamin A deficiency, congenital stationary night blindness (CSNB), Oguchi disease or RP, diseases that are directly linked to the malfunction of Arrestin-1 and GRK1, and Rhodopsin and Transducin-α." (PMID 36766830, 2023). "For example both SAG and GRK1 in addition to an association with PRC thickness have a known involvement in Oguchi disease, a rare autosomal eye condition which causes visual impairment." (PMID 36848389, 2023). "On the other hand, GRK1 gene mutations are mostly found in southern Asians and Europeans patients with Oguchi disease, with very few reports of families harboring SAG gene mutations." (PMID 35549688, 2022). "In this study, we present a Pakistani family (RP19) with Oguchi disease in whom we found a causative novel protein-truncating mutation in the GRK1 gene (p.S205X)." (PMID 19753316, 2009). "These mutations are mainly associated with Oguchi disease, although one report describes the association of GRK1 mutations with retinitis pigmentosa (RP)." (PMID 19753316, 2009). "Because mutations in GRK1 are mainly associated with Oguchi disease, clinical characteristics of the affected family members were reevaluated." (PMID 19753316, 2009). "The middle column shows responses from a patient with GRK1‐associated Oguchi disease." (PMID 40013354, 2025). "Initially developed as a treatment for Oguchi disease, which occurs in individuals with rod opsin and GRK1 mutations that prevent phosphorylation, these arrestin mutants have their ‘phosphorylation sensor’ removed, increasing their affinity for photoactivated unphosphorylated opsin." (PMID 38036775, 2023). "Indeed, SAG mutations are concentrated in Japanese patients of Oguchi disease while GRK1 mutations are very rarely reported in Japanese patients." (PMID 35549688, 2022). "Oguchi disease-2 is caused by mutation in the rhodopsin kinase gene (GRK1) on chromosome 13q34." (PMID 35246075, 2022). "Oguchi disease is associated with bi‐allelic pathogenic variants in GRK1 or SAG." (PMID 35612091, 2022). "Light damage in Arr1 and Grk1 knock-out mice, both associated with Oguchi disease, was extremely robust, but could also be fully prevented with increasing doses of MET+BRM+TAM." (PMID 30947334, 2019). "Patients with Oguchi disease could be at an even higher risk of these damaging light effects as the Grk1−/− and Arr1−/− mice were extremely sensitive to light damage." (PMID 30947334, 2019). "The DA red flash ERG can also help determine the origin of residual DA ERGs in cases of severe rod dysfunction, for example in disorders such as vitamin A deficiency, fundus albipunctatus (RDH5-retinopathy), Oguchi disease (SAG- or GRK1-retinopathy) and some rod-cone dystrophies." (PMID 29934801, 2018). "In addition to the GRK1 missense, null and frameshift mutations identified by different groups, many Oguchi disease patients have been shown to carry deletions of one or more exons of the gene." (PMID 19753316, 2009). "Oguchi disease has been found to be associated with gene mutations in SAG and GRK1, which are vital factors in the recovery phase of phototransduction after light stimuli." (PMID 35246075, 2022). "This occurs, for example, in vitamin A deficiency, fundus albipunctatus (RDH5-retinopathy) and Oguchi disease (SAG- or GRK1-retinopathy) and in some cases of rod-cone dystrophy including early stages of Bothnia dystrophy (RLBP1-retinopathy)." (PMID 29934801, 2018).
Oguchi disease (continued). "A variant form of Oguchi disease has also been reported to be caused by a deletion in exon 3 of the GRK1 gene without the typical Mizuo-Nakamura phenomenon in the affected individual." (PMID 19753316, 2009). "Two known genes in pathogenesis of Oguchi disease are SAG and GRK1." (PMID 32953689, 2020). "Patients lacking GRK1 or arrestin suffer from Oguchi disease, a form of stationary night blindness, which is not characterized by rod cell death." (PMID 24301679, 2014). "Oguchi disease has not been described so far in the Egyptian population or in any African population, and the mutation spectrum remains unknown whether SAG or GRK1 mutations will prevail." (PMID 35549688, 2022). "No studies reported any patients with Oguchi disease in Egyptian or African population, and it remained unclear whether they harbor SAG gene or GRK1 gene mutations." (PMID 35549688, 2022).
congenital stationary night blindness (7 papers, 2014 to 2025). "Biallelic mutations in G‐Protein coupled receptor kinase 1 (GRK1) cause Oguchi disease, a rare subtype of congenital stationary night blindness (CSNB)." (PMID 33252155, 2021). "Variants in LRIT3, GRK1, and RLBP1 were previously reported to be associated with autosomal recessive or X-linked congenital stationary night blindness." (PMID 40365019, 2025). "Integrated expression and transcription regulatory network genes, such as congenital stationary night blindness (CSNB) genes GRK1, PDE6B, and TRPM1, showed cell-specific expression and transcription characteristics in either rods or bipolar cells (BCs)." (PMID 39055259, 2024). "Six genes encoding major components of the phototransduction cascade (RHO, GNAT1, PDE6B, GRK1, and SAG) and the regeneration of the visual pigment (RDH5) are described in congenital stationary night blindness (CSNB) patients." (PMID 24760071, 2014).
retinal disease (5 papers, 2004 to 2022). "Screening of inherited retinal disease patients by an international consortium of retinal genetics laboratories identified 12 cases with Oguchi disease harboring nine different disease associated variants in GRK1, of which eight are previously unreported." (PMID 33252155, 2021). "Here, the interaction of Hsp90 with the retina-specific client proteins PDE6 and GRK1 will be further discussed, providing additional insights for the role of Hsp90 in retinal disease." (PMID 35883534, 2022). "Future gene therapy vectors for treatments of inherited retinal disease are therefore likely to contain the GRK1 promoter, and being able to test such vectors in retinal organoids would be highly desired." (PMID 35377942, 2022). "In this category, other interesting results are represented by the discovery of two different subjects carrying biallelic LoF variants in the GRK1 and RP1L1 genes, both involved in retinal diseases." (PMID 33727708, 2021).
Rod-cone dystrophy (4 papers, 2015 to 2024). An inherited retinal disease subtype in which the rod photoreceptors appear to be more severely affected than the cone photoreceptors. "In PR cells, PrBP/δ traffics prenylated cargo such as PDE6, Rab28, and rhodopsin kinase (GRK1) from the site of protein synthesis (inner segment) to the retinal outer segment, and its homozygous deletion causes slow, progressive rod-cone dystrophy." (PMID 39026984, 2024). "A PDEδ knockout mouse develops a more subtle phenotype with a slowly progressive rod-cone dystrophy together with mislocalisation of prenylated phototransduction proteins such as rhodopsin kinase (GRK1) and the catalytic subunits of rod and cone cyclic GMP phosphodiesterase (PDE6)." (PMID 26093275, 2015).
Oguchi disease-2 (3 papers, 2009 to 2022). Any Oguchi disease in which the cause of the disease is a mutation in the GRK1 gene. "In our study, molecular screening of the 7 coding exons of the GRK1 gene revealed normal sequence excluding Oguchi disease type 2." (PMID 35549688, 2022). "Mutations in arrestin gene (SAG, S-antigen; OMIM:181031) were first discovered in Japanese patients (Oguchi disease type 1), later on, mutations involving the rhodopsin kinase gene (GRK1; OMIM:180381) were implicated in European patients (Oguchi disease type 2)." (PMID 35549688, 2022).
retinal degeneration (3 papers, 2019 to 2026). Degeneration of the retina. "Rp2-deficient mice exhibit defects in trafficking of GRK1 as well as rod and cone PDE6 to the outer segment, and subsequent slowly progressing retinal degeneration." (PMID 33681987, 2021). "Consistent with Unc119 and Pde6d deficiency, Arl3 conditional knockout mice show trafficking defects of lipidated proteins including rTα, rTγ, rod PDE6 and GRK1 to outer segments in rod photoreceptors and subsequent retinal degeneration." (PMID 33681987, 2021).
breast carcinoma (2 papers, 2019 to 2024). "First of all, we dissected the transcriptional profiling of GRK subfamily members (GRK1-7) in primary tumors and normal mammary epithelial tissues from TCGA breast cancer database." (PMID 39741338, 2024).
embryonal carcinoma (2 papers, 2022 to 2025). A non-seminomatous malignant germ cell tumor characterized by the presence of large germ cells with abundant cytoplasm resembling epithelial cells, geographic necrosis, high mitotic activity, and pseudoglandular and pseudopapillary structures formation. "A recent analysis of the Cancer Genome Atlas demonstrated that KIT, KRAS, and NRAS gene variants were observed only in seminoma, while gene variants in B3GNT8, CAPN7, FAT4, GRK1, TACC2, and TRAM1L1 occurred only in embryonal carcinoma." (PMID 41426877, 2025). "Mutations in ADAMTS20, ARHGAP10, OR1L4, PDS5A, and RPLP0 were only found in mixed germ cell tumors, while mutations in B3GNT8, CAPN7, FAT4, GRK1, TACC2 and TRAM1L1 were only observed in embryonal carcinoma, and their mutation frequency was around 2%." (PMID 36713456, 2022). "As described in our results, mutation that only occurs in embryonal carcinoma (B3GNT8, CAPN7, FAT4, GRK1, TACC2 and TRAM1L1) or seminoma (KIT, KARS and NRAS) may be valuable molecular markers and therapeutic targets that need to be considered clinically." (PMID 36713456, 2022). "Differences in somatic mutations between subtypes are also of concern, with our results suggesting that mutations in some genes (B3GNT8, CAPN7, FAT4, GRK1, TACC2, and TRAM1L1) occur only in embryonal carcinoma, while mutations in KIT, KARS, and NRAS are observed only in seminoma." (PMID 36713456, 2022).
night blindness (2 papers, 2014 to 2025). Inability to see clearly in dim light. "These visual symptoms, in particular night blindness and visual impairment, could be due to reductions in PDE and GRK1." (PMID 24301679, 2014).
cardiac hypertrophy (1 paper, 2014). "Regardless, the GRK1·amlexanox structure will serve as a useful platform to begin rational design of amlexanox-based therapeutics for the treatment of either cardiac hypertrophy (GRK5) or, by extension, diabetes (IKKε)." (PMID 25340299, 2014).
lung squamous cell carcinoma (1 paper, 2023). "GRk1 was also reported to have anti-tumor activity against lung squamous cell carcinoma, and at 30 mg/kg, GRk1 injections markedly inhibited tumor xenograft growth." (PMID 38139116, 2023).
cancer (4 papers, 2017 to 2021). A tumor composed of atypical neoplastic, often pleomorphic cells that invade other tissues. "Briefly discussing the role of GRKs in cancer, GRK1 and GRK7 were shown to play a role in embryogenesis, while interacting indirectly with Rho GDP-dissociation inhibitor (RhoGDI) and phosphodiesterase γ (PDEγ), both of which are shown to be abnormally regulated in cancer." (PMID 33806057, 2021).
infection (2 papers, 2013 to 2023). The state of being infected such as from the introduction of a foreign agent such as serum, vaccine, antigenic substance or organism. "This occurs because IL-33 inhibits G protein-coupled receptor kinase-1 (GRK-1) downregulation which is induced by TLR signaling during infection by bacteria or fungi." (PMID 23653627, 2013).
retinopathy (2 papers, 2018 to 2021). "Dark-adapted red flash ERGs aid diagnosis of rod- and S-cone monochromacy, cone dystrophy, vitamin A deficiency, RDH5-retinopathy, SAG- or GRK1-retinopathy, some cases of rod-cone dystrophy, RGS9- and R9AP-retinopathy and colour vision deficiencies." (PMID 34045684, 2021).
GRK1 also shares sentences with these, for which no sentence is quoted: tumor (4 papers); hepatocellular carcinoma (2); Insulin resistance (2); liver cancer (2); seminoma (2); vitamin A deficiency (2); amnesia (1); Arthritis (1); asthma (1); autosomal recessive congenital stationary night blindness (1); breast adenocarcinoma (1); cervical cancer (1); Chudley-McCullough syndrome (1); colon cancer (1); diabetes (1); fundus albipunctatus (1); gastric cancer (1); Hypertension (1); influenza (1); liver disease (1); lung carcinoma (1); melanoma (1); mixed germ cell tumor (1); myopia (1); Oguchi disease type 1 (1); pancreatic cancer (1); pituitary hormone deficiency (1); retinitis pigmentosa (1); schizophrenia (1); virus infection (1).
A further 1 disease shares a sentence with GRK1 in 1 paper.